PAIP1 (poly(A) binding protein interacting protein 1)
Description:
Acts as a coactivator in the regulation of translation initiation of poly(A)-containing mRNAs. Its stimulatory activity on translation is mediated via its action on PABPC1. Competes with PAIP2 for binding to PABPC1. Its association with EIF4A and PABPC1 may potentiate contacts between mRNA termini. May also be involved in translationally coupled mRNA turnover. Implicated with other RNA-binding proteins in the cytoplasmic deadenylation/translational and decay interplay of the FOS mRNA mediated by the major coding-region determinant of instability (mCRD) domain. (Microbial infection) Upon interaction with SARS coronavirus SARS-CoV NSP3 protein, plays an important role in viral protein synthesis.
Tractability: Antibody: the Human Protein Atlas places it where antibodies can reach. PROTAC: ubiquitination databases record sites on it; its protein half-life has been measured.
Gene: Protein-coding gene on chromosome 5 (43,526,267 to 43,557,758, reverse strand). Ensembl gene ENSG00000172239.
Subcellular location: Cytoplasm
Subcellular location (Human Protein Atlas): Cytosol; Plasma membrane
Pathways (Reactome):
Developmental Biology: M-decay: degradation of maternal mRNAs by maternally stored factors; Z-decay: degradation of maternal mRNAs by zygotically expressed factors
Metabolism of RNA: Deadenylation of mRNA
Gene Ontology:
Molecular function: protein binding; translation activator activity; RNA binding
Biological process: CRD-mediated mRNA stabilization; host-mediated activation of viral process; negative regulation of nuclear-transcribed mRNA catabolic process, deadenylation-dependent decay; positive regulation of cytoplasmic translation; mRNA stabilization; regulation of translational initiation; translational initiation
Cellular component: cytosol; mCRD-mediated mRNA stability complex; plasma membrane; cytoplasm
Genetic constraint (gnomAD): Loss-of-function variants: 8 observed, 7.67 expected, observed/expected ratio (o/e) 1.04, 90% interval 0.61 to 1.76. That is too few expected variants to judge how well the gene tolerates losing a copy. Missense variants: 198 observed, 137.4 expected, observed/expected ratio (o/e) 1.44, 90% interval 1.28 to 1.62. Synonymous variants: 95 observed, 58.8 expected, observed/expected ratio (o/e) 1.62, 90% interval 1.37 to 1.89.
Homologues: Orthologues: chimpanzee PAIP1 (99% identical), macaque PAIP1 (99% identical), pig PAIP1 (97% identical), rat Paip1 (96% identical), rabbit PAIP1 (96% identical), guinea pig Paip1 (80% identical), mouse Paip1 (75% identical), dog PAIP1 (70% identical), tropical clawed frog paip1 (68% identical), zebrafish paip1 (50% identical), Drosophila melanogaster Paip1 (25% identical). Paralogues in human: CTIF (17% identical), MIF4GD (10% identical).